RHOA (ras homolog family member A)
Diseases named in the same sentence as RHOA in open-access papers (continued):
Sharing a sentence is not in itself a finding about the gene and the disease.
cancer (continued). "ANLN (Anillin) encodes a key regulator of cytokinesis that acts as a scaffold protein to facilitate RhoA pathway activation and contractile ring assembly, ensuring successful cell division; ANLN overexpression promotes proliferation in cancer cells." (PMID 41246267, 2025). "We have shown previously that the PCAIs suppress the levels of RAC1, RHOA, and CDC42 in cancer cell lines." (PMID 40736275, 2025). "These protrusions are dependent on the actin-polymerizing protein FMNL1, and Rab25 coordinates the activity of RhoA with the arrival of FMNL1 and integrin β1 cargos to form protrusions that promote invasive migration of cancer cells in the 3D matrix." (PMID 40614209, 2025). "Overall, these results show how Ect2 and anillin cooperate to mediate RhoA/ROCK/myosin II-dependent mechanoadaptation and invasive cancer progression." (PMID 40571734, 2025). "FTase proteins (FNTA and FNTB) as well as eight of the 116 PFPs are known cancer-relevant proteins as per COSMIC Cancer Gene Census49 or TCGA50 (KRAS, HRAS, NRAS, RHEB, RHOA, DDX3X, ARID2, and SAV1)." (PMID 39995872, 2025). "The breakthrough findings of the importance of RhoA/MRTFs/SRF transcription in cardiovascular, neurodegenerative, and intestinal diseases and fibrosis to cancer tumorigenesis and metastasis have been much appreciated." (PMID 38474356, 2024). "Previous studies revealed that ARHGEF5 regulates actin cytoskeletal dynamics by activating the RhoA-ROCK pathway, thereby promoting the migration and invasion of cancer cells." (PMID 38932934, 2024). "In our study, we show that 10C7 treatment of BT-20 cells potentiated the level of active RhoA thus demonstrating that 10C7 effectively binds endogenous GPR56 and retains function in cancer cells." (PMID 39281883, 2024). "Disruption of the NEK2–RhoGDI1 interaction through overexpression of a RhoGDI1 truncated fragment (aa 112–134) led to diminished RhoGDI1 phosphorylation and RhoA/Rac1 activation induced by NEK2, resulting in reduced cancer cell proliferation and migration." (PMID 39768163, 2024). "Recently, CNTN1 has been reported to mediate cell functions involving multiple signaling pathways, including the Notch signaling pathway, RHOA dependent pathway, RET/PTC3 pathway, and VEGFC/FLT4 axis to promote the invasion and metastasis of cancer cells." (PMID 38562021, 2024). "Overall, our work provides a mechanistic understanding of how cytokinesis regulators mediate RhoA/ROCK/myosin II-dependent mechanoadaptation during confined migration and invasive cancer progression." (PMID 38260442, 2024). "A recent study has shown that RhoA/ROCK plays a vital role in promoting the translocation of GLUT1 to the PM and then enhancing glucose uptake of cancer cells." (PMID 38706741, 2024). "The data indicate that a Syx-RhoA-Dia1-YAP/TAZ signaling axis regulates cell cycle progression, DNA damage, and therapy resistance in GBM and argue for its targeting for cancer treatment." (PMID 37427593, 2023). "Cancer cells release CTHRC1 into their microenvironment, enhancing their motility and the motility of neighboring cancer cells by activating RhoA signaling." (PMID 37273536, 2023). "This is the case of RhoA/ROCK and JUNB signaling pathways that regulate NFIX expression during myogenesis and are involved in cancer cell proliferation and invasion." (PMID 36901722, 2023). "We therefore concluded a stimulatory effect of EV-associated ROR1 and ROR2 on cancer cell invasion requiring the presence of RhoA without significantly upregulating its expression.We next analyzed whether EV uptake was required for the invasion-promoting effect of ROR-EVs." (PMID 37430307, 2023). "Truncations of Tmod3 induced by AEP contribute to cancer progression by facilitating actin remodeling and nuclear SND1 mediated RhoA/CDKs transcription." (PMID 35765111, 2022).
cancer (continued). "After incubation with hypoxic-derived exosomes, prometastatic signals can be transmitted to normoxic cancer cells, resulting in overexpressed GEF-H1/RhoA and increased cell migration capacity." (PMID 36238299, 2022). "We have learned that RhoA is an upstream regulator of SRF-MRTFA, a potential therapeutic target for malignant tumors, and further activates the expression of G-actin, F-actin, and other transcription factors in cancer cells." (PMID 35075114, 2022). "Some of these proteins, specifically RhoA, Vimentin, LDHA and are very important proteins in the development and progression of cancer." (PMID 36313672, 2022). "We also observed the significant inhibition of miR-31-targeted genes following GBK treatment, including RHOA, WAVE3, and SATB2, with functions closely related to cancer cell invasion, migration, and proliferation." (PMID 36313626, 2022). "In summary, our findings reveal a role for RhoA-mediated signaling and gene expression during the outgrowth of residual EGFR-mutant cancer cells in the brain and progression of CNS metastases under osimertinib treatment." (PMID 36509758, 2022). "The result demonstrated a significant value of VAV1, RHOA, and ZC3HAV1 in predicting the therapeutic efficacy of ICIs for patients with various cancer types." (PMID 36224658, 2022). "These two truncations played completely different roles in promoting cancer than those exhibited by Tmod3 through actin remodeling and SND1/RhoA-mediated cell proliferation." (PMID 35765111, 2022). "Mechanistically, KIBRA suppresses RhoA activation, impairing the nuclear translocation of the oncogenes, and YAP/TAZ, which drives metastatic and cancer stem-cell-like behavior." (PMID 34441043, 2021). "Pre-mRNA processing factor 4B (PRP4) is overexpressed in HCT116 colon cancer cells by inhibiting RhoA activity and inducing cofilin dephosphorylation by inhibiting the Rho-ROCK-LIMK cofilin pathway and regulating the actin skeleton of cancer cells." (PMID 33816252, 2021). "We will focus in particular on five members of the RHO GTPase family, including RHOA, RHOB, RHOC, RAC1, and CDC42, to illustrate the role of lncRNAs in cancer progression." (PMID 34771549, 2021). "Elimination of the phosphorylation of Thr359 decreased RhoA activation and epithelial–mesenchymal transition (EMT), which resulted in the inhibition of the proliferation of malignant cancer cells." (PMID 33546351, 2021). "Targeting DNMT, and in the majority of cases also RhoA, in combination with SRC-3 inhibition, was effective across the cancer lines that have been tested." (PMID 33767353, 2021). "To verify that cancer stemness is dependent on amoeboid Rho/ROCK signaling, we treated control and RASSF1C spheroids in 3D collagen matrix with either a RhoA (C3) or a ROCK inhibitor (Y27632)." (PMID 34532864, 2021). "Our study lays the foundation for more comprehensive experimental study (in vitro, in vivo) on modulating the cell death drug targets FANCD2, NCOA4 (COAD), IKBKB, (GBM), and RHOA (GBM and SCLC), to improve the therapeutic avenues in cancer treatment." (PMID 33670487, 2021). "While in some cancer cell lines TRPV2 seems to have a positive impact on cancer cell migration, the interplay between TRPV2 and RhoA/Rac1 seems to suppress invasion of Fibroblast-like Synoviocytes (FLS cells)." (PMID 34356643, 2021). "AFAP1-AS1 can indirectly influence activity of some cancer-related pathways such as EGFR/AKT, Wnt/β-catenin, PTEN/p-AKT, RhoA/Rac2 and PI3K/AKT." (PMID 34912717, 2021). "In this study, we show for the first time that ALPL inhibits the metastasis of LUAD cells via the p-ERK1/2-c-Myc-RhoA axis, which extends our understanding of the role of ALPL in cancer development." (PMID 33858415, 2021). "Consistently, our model suggests that in cancer cells where p97/VCP is more abundant, RhoA level turnover is misregulated." (PMID 32002125, 2020).
cancer (continued). "ROCKs are major effectors of the small GTPase RHOA, and the important roles of ROCK in cancer progression, including in cell metastasis, have been demonstrated by thousands of studies." (PMID 32550827, 2020). "We showed that phosphorylation of ARHGAP18 by PKN3 leads to activation of its GAP domain and contributes to regulation of active RhoA levels, implying the possible crosstalk of PKN3 and ARHGAP18 signaling in cancer and other diseases." (PMID 33092266, 2020). "RhoA overexpression was correlated with significantly worse DFS and DMFS rates (P = 0.045 and P = 0.041, respectively) in stage III cancer patients." (PMID 31976530, 2020). "Targeting the major downstream effector of RhoA, Rho-kinase (ROCK) is a promising cancer therapeutic approach." (PMID 32443784, 2020). "To date, studies on how RhoA and GEF-H1 regulate cancer cell migration have shown different results in a cell line–dependent pattern." (PMID 32789168, 2020). "In vitro experiments showed that RhoA overexpression together with ROCK1 and ROCK2 supported spreading and migration of HeLa cells, meaning a higher metastatic potential of cancer cells." (PMID 32443784, 2020). "In this review, we will explore the relationships between VEGFs, their receptors, and the Rho GTPases, highlighting the involvement of RhoA, RhoC, and RhoG in VEGF signaling and the formation of new blood vessels in cancer." (PMID 32377503, 2020). "Previous studies have validated that high expression of RHOA and ROCK is frequently reported in various cancer-types, such as breast cancer, ovarian cancer and colon cancer." (PMID 31820783, 2020). "Conversely to RHOA and RHOC, RHOB has been described to be downregulated in several malignancies where its expression promotes apoptosis in cancer cell lines and inhibits invasion." (PMID 31888022, 2019). "The reduced RhoA activity resulted in increased expression of the cognate receptor, CXCR4, for CXCL12 in 4T1 cancer cells." (PMID 31705019, 2019). "Migration and invasion are responsible for much of the malignant character of GBM and other cancers, and TGF-β is well-known to promote these behaviors through mediators such as RhoA and ROCK." (PMID 30899443, 2019). "This is in accordance with previous reports which described antagonistic roles of the 2 isoforms RHOA and RHOC, albeit during cancer cell invasion." (PMID 30781697, 2019). "In agreement with this line of reasoning, we observed the expression levels of CCR5 were increased in RhoA knockdown tumors and the increased CCR5 expression levels are partly due to an increase in CCR5 transcripts in cancer cells." (PMID 31705019, 2019). "Specifically, levels of the pVHL and RhoA were decreased, and the expression of HDAC1, CD44 (a cancer stem cell [CSC] marker), Snail, and vimentin (EMT markers) in normal hRECs and various renal tumor cell types (Caki-2, ACHN, and 798-o) was upregulated." (PMID 30872677, 2019). "The activation of RhoA/ROCK in cancer cells activates MLC and increases migration, while the genetic-down-regulation of RhoA and pharmacological inhibition of ROCK reduced cell scattering and invasion." (PMID 29535813, 2018). "Two distinct mechanisms induced the activation of the RhoA/ROCK pathway in MDA-MB-231 cells, the secretion of IGF-1 by CAFs and the upregulation of PAI-1 in cancer cells." (PMID 29535813, 2018). "The mechanism of β-elemene to inhibit cancer or other diseases has been proven to be involved in many pathways, such as BMP/SMADs pathway, RhoA/ROCK pathway, and canonical Wnt/β-catenin pathway." (PMID 29358311, 2018). "IPA analysis of the 382 enhancer-assigned genes showed that the most significantly enriched pathways were cancer-related pathways, such as NRF2-mediated oxidative stress response, TNFR2 signaling, RhoA signaling, and IL-1 signaling." (PMID 30005692, 2018). "Some of the players found to be affiliated with EMT and cancer stem-like cell maintenance include the PI3K/AKT pathway, RhoA, VEGFR, SOX2 and Wnt/β-catenin and SHH pathways." (PMID 29298329, 2018).
cancer (continued). "Hypoxia-induced upregulation of supervillin promoted cancer cell migration and invasion via the activation of the ERK/p38 pathway downstream of RhoA/ROCK signaling." (PMID 29954442, 2018). "Previous studies have documented that integrin α5β1 confers invasiveness to cancer cells by regulating the MMP-2 activity and integrin β1 signaling is capable of suppressing RhoA activity and activating MMP-2-dependent cell migration." (PMID 28977889, 2017). "By targeting DNMT1, RhoA/Cdc42, and E2F6, miR-185 has been shown to induce cell cycle arrest and apoptosis, in addition to inhibiting proliferation and invasion in cancer cell lines and xenograft mouse models of various cancers." (PMID 26930719, 2016). "Zinc-treated cells exhibited the mesenchymal-like morphology and increased cancer cell motility with significant increase of activated FAK, Rac1, and RhoA." (PMID 27330411, 2016). "Statins are known to reduce cell proliferation via down-regulation of critical signaling pathways in a few human cancers, including AKT/mTOR, MAPK, JAK2/STAT3, Ras, NF-κB, JUNK and RhoA/ROCK pathways." (PMID 26503475, 2016). "Immunohistochemical staining showed that CXCR4, RhoA, RhoGEF, ARHGAP5, PI3K, ROCK, PAK and PKN were significantly up-regulated in cancer tissues compared with normal tissues." (PMID 27517626, 2016). "Leptin exposure increased cancer cell migration/invasion through leptin-mediated activation of JAK/STAT3, PI3/AKT and RhoA/ROCK and promoted new lamellipodial, stress-fiber and focal adhesion formation." (PMID 26053184, 2015). "We studied how the Rho GTPases mediated SDF-1α effect, by demonstrating that RhoA and Rac1 were sequentially activated at different concentration of SDF-1α, thus, promoting different metastatic properties through the modulation of cancer cells phenotype." (PMID 26231656, 2015). "The RhoA/ROCK pathway and Caveolin-1 (Cav-1) participate in the process of tumorigenesis in numerous types of cancer." (PMID 26066055, 2015). "We have recently reported that ZA effectively interrupts Ras- and RhoA-dependent downstream signalling pathways, abrogates Pgp expression, and restores Doxo-induced cytotoxicity in MDR+ human cancer cell lines derived from solid tumors." (PMID 26284584, 2015). "Both C4-2-B2 and PC-3 cells are cancer cells and, as compared to normal cells such as RWPE-1, exhibit higher level of RhoA." (PMID 24683532, 2014). "Activity of Rho GTPases is elevated in many human cancers and their metastases, and the oncosuppressive effect of DLC1 requires RhoGAP activity, which negatively regulates Rho GTPases, most commonly RhoA." (PMID 23607551, 2013). "For example, deletion of liver cancer 1 (DLC-1), a RhoA and Cdc42-specific GAP, inhibits the growth of various types of cancer, including lung, breast, prostate, kidney, colon, uterus, ovary and stomach through altering the actin cytoskeleton." (PMID 23538840, 2013). "Some reports indicate that RhoA, RhoC and their downstream target ROCK are needed for cancer cell extravasation." (PMID 20822528, 2010). "Collectively, these results show that cells with high integrin-RhoA/YAP activity and MMP14 function act as leaders that drive microchannel network construction, while coinhibiting either pathway significantly inhibits cancer metastasis." (PMID 41417886, 2025). "Additionally, PDPN modulates the activities of Rho-family GTPases, particularly RhoA, which contributes to the pro-migratory phenotype of PDPN-expressing cancer cells." (PMID 40666093, 2025). "Through RhoA regulation, GMIP impacts cytoskeletal stability and reorganisation, affecting cell morphology, migration, division and adhesion—key processes in tissue development, wound healing and cancer metastasis." (PMID 40275529, 2025). "Additionally, the TISCH2 indicated that all the hub-genes of cancer cells were upregulated in malignant cells, especially GAPDH, RHOA, TPI1, H4C6, DDX21, and APEX1, which showed considerably high expression levels in malignant cells." (PMID 40906153, 2025).
cancer (continued). "Gene expression analysis suggests that its mechanism of action may involve downregulation of cancer-related genes such as AKT1, BCL2L1, CCND1, CDK4, PLK1, and RHOA." (PMID 38751791, 2024). "These outcomes suggest that the precise role of RhoA/ROCK and y-27632 may be unclear and cell- and cancer-type specific." (PMID 38921484, 2024). "For example, in human cancer cell lines ephrinB1 interacts with RhoGDI1 through its cytoplasmic domain which limits the activity of RhoA in the absence of ephrinB1 interaction with the EphB2 receptor." (PMID 39086660, 2024). "Rgnef’s unique ability to bind focal adhesion kinase (FAK) via its C-terminus–a feature not shared with other GEFs–has important implications for cancer progression via FAK/RhoA/paxillin signaling." (PMID 39493347, 2024). "Notably, the relationship between CEP55 and RhoA/ROCK1 signaling has been discovered, with a focus on therapeutic consequences in cancer." (PMID 39023191, 2024). "We further investigated how 4-carbomethoxyl-10-epigyrosanoldie E impacts the levels of proteins such as FAK, PKC, GRB2, Rac, Ras, RhoA, MEKK3, and MKK7, which are upstream regulators in the MAPK pathway and play a role in controlling the expression of MMPs involved in cancer cell metastasis." (PMID 38374934, 2024). "Although Rac is considered to antagonize RhoA, studies suggest that RACGAP1 can keep Rac or RhoA activated in different cancers, and the subsequent events of Rac and RhoA activation are not always irrelevant, implying that RACGAP1 can coordinate Rac and RhoA in some situations." (PMID 39858398, 2024). "We previously used intravital FLIM-FRET multiphoton microscopy to measure Rac activity in live Rac-FRET mice in cancer models, and we used RhoA-FRET LysMCre mice in a similar manner to measure RhoA activity during S. aureus-induced neutrophil swarming in the skin." (PMID 37383235, 2023). "Unlike other members of Rho family, like RhoA and RhoC, which play oncogenic roles, RhoB has been shown to suppress tumorigenesis in pancreatic and other cancers." (PMID 37794133, 2023). "In the present study, we demonstrate that AEP specifically cleaves Tmod3 at N157 and produces two truncated Tmod3 proteins, which regulate the invasion and proliferation of cancer cells through cytoplasmic actin remodeling and nuclear SND1/RhoA signaling, respectively." (PMID 35765111, 2022). "RhoA also is involved in membrane folding, formation of plasma membrane vesicles, and stress fiber formation by affecting ROCK and mDia; it plays a role in the formation of the leading edge protrusion of cancer cells." (PMID 35619906, 2022). "It has been reported that RhoA and Rac1 signaling pathways promote EMT in malignant tumors." (PMID 35075114, 2022). "In order to demonstrate the direct involvement of miR-31 in the regulation of these genes in cancer cells, we tested the effect of miR-31 mimics and inhibitor on the expression of STAB2, RHOA, WAVE3 and other relative genes after transfection into MCF-7 and SUM-159 cells." (PMID 36313626, 2022). "Moreover, increased ECM stiffness drives β1 integrin-FAK signaling, which in turn, activates RhoA/ROCK1/MLC and RhoA/ROCK2/cofilin signaling cascades toward cancer cell motility." (PMID 35163650, 2022). "Unraveling the mechanism by which RhoA modulates DDR may provide more insight into DDR itself and may aid in the future development of cancer therapies." (PMID 33546351, 2021). "In concordance with the RhoA activity results, we found that the overexpression of ARHGAP35 protein significantly reduced actin‐based stress fiber formation and RhoA function in cancer cell lines, while overexpression of circARHGAP35 protein slightly increased stress fiber formation." (PMID 34258149, 2021). "This adds to our understanding of the functions of RhoA and the detailed mechanisms of DDR, which may provide assistance in overcoming chemoresistance in cancer therapies." (PMID 33546351, 2021).